S100B (S100 calcium binding protein B)
Diseases named in the same sentence as S100B in open-access papers (continued):
Sharing a sentence is not in itself a finding about the gene and the disease.
cardiac arrest (continued). "Finally, a Turkish study evaluated the predictive utility of NSE, S100B, and procalcitonin after resuscitated cardiac arrest, and found that high S100B levels at admission had higher sensitivity than NSE levels; however, it did not assess multimodal prognostication." (PMID 35566469, 2022). "In the present study, we evaluated the correlation between NSE, serum S100B, and EEG patterns in pediatric patients with in-hospital cardiac arrest circumstances and assessed patient outcomes, including the duration of CPR and survival." (PMID 36832309, 2023). "A prospective observational study was conducted in the pediatric intensive care unit and included 41 post-cardiac arrest patients who underwent EEG and serum sampling for NSE and S100B." (PMID 36832309, 2023). "For the post-cardiac arrest comatose state, the serum markers of neuronal injury NSE and S100B within 48–72 h are useful for prognostication." (PMID 28035993, 2016). "We also carried out, to our knowledge, the first comparative study of serum levels of NSE, S100β, and MBP in critically ill infants and children after TBI, AHT, and cardiopulmonary arrest." (PMID 23637695, 2013). "In addition to NSE and S100B, several emerging neurobiomarkers—such as neurofilament light chain (NfL), Tau, and glial fibrillary acidic protein (GFAP)—have shown promise for outcome prediction after cardiac arrest." (PMID 40759951, 2025). "However, mild therapeutic hypothermia did not affect S100B serum levels in survivors of cardiac arrest in several clinical studies." (PMID 20158893, 2010). "Because S100β and GFAP were not selected for analysis, glial disintegration by cardiac arrest was not assessed in this study." (PMID 28950909, 2017). "S100B has been used as a marker to rule out intracranial injury in mild traumatic brain injury to avoid unnecessary computer tomography scans and NSE has been used as a prognostic factor in adverse neurological outcome after cardiac arrest." (PMID 33556141, 2021). "While NSE and S100B are increased in the setting of hemolysis - frequently occurring during ECMO treatment - these novel markers might overcome this limitation, but remain yet to be evaluated in ECMO patients not suffering from cardiac arrest." (PMID 39695311, 2024).
glioma (47 papers, 2010 to 2025). A benign or malignant brain and spinal cord tumor that arises from glial cells (astrocytes, oligodendrocytes, ependymal cells). "We also examined the expression of AQP-4 and S100B, which are frequently associated with glioma malignancy." (PMID 41154863, 2025). "Researchers have found that S100B promotes glioma growth via tumor-associated macrophages and that the suppression of S100B inhibits glioma growth." (PMID 33585189, 2020). "A previous pilot study showed that high serum levels of S100B are associated with shorter survival in glioma patients." (PMID 27401156, 2016). "Adding S100B to cells containing either wild type Thioredoxin or mutated TSc induces normal RAGE signaling in both C6 glioma and VSMC cells." (PMID 23785412, 2013). "The RAGE pathway may play an important role in STAT3 induction in glioma-associated microglia and macrophages, a process that might be mediated through S100B." (PMID 24521265, 2013). "S100B can also maintain immunosuppressive microenvironmental characteristics of gliomas by chemotaxis of TAMs through the upregulation of CCL2." (PMID 40243478, 2025). "In these subtypes, AC-like glioma cells express some characteristic astrocyte markers, such as S100B, GFAP, SLC1A3, GLAST, and MLC1." (PMID 40243478, 2025). "Further, the S100B protein regulates astrocyte shape and migration in human glioma cells, as reducing its levels in GL15 by Small interfering RNA technique reduces migration and acquisition of a stellate shape." (PMID 39027325, 2024). "On the other hand, S100B concentrations in the nanomolar range stimulate glial cell proliferation and inhibit differentiation of rat C6 glioma cells and primary astrocytes." (PMID 39027325, 2024). "To more closely examine the observed difference in S100B secretion related to oxidative metabolism, we evaluated glucose uptake in and lactate release into the extracellular medium in C6 glioma cells and hippocampal slices in the presence of FC." (PMID 38276297, 2023). "Despite the difference in S100B secretion between C6 glioma cells and acute hippocampal slices, we evaluated other astroglial parameters in C6 cells exposed to FC, such as glutamate uptake, glutamine synthetase activity and GSH content." (PMID 38276297, 2023). "A few years ago, we observed that astrocytes and C6 glioma cells expressed and secreted S100B in an opposite way when exposed to a medium with high glucose." (PMID 38276297, 2023). "Herein, we investigate the impact of FC on S100B secretion in primary astrocyte cultures, acute hippocampal slices and C6 glioma cells, as well as lactate mediation." (PMID 38276297, 2023). "FC promoted increased S100B secretion in C6 glioma cells, while in reduced in astrocyte cultures and acute hippocampal slices." (PMID 38276297, 2023). "For both astrocytes and C6 glioma cells, S100B is constitutively secreted and can, in situations of injury, be more actively released, acting as an alarmin on RAGE, the receptor for both glycation end-products and S100B itself." (PMID 38276297, 2023). "In fact, the S100B secretion profiles were opposite for C6 glioma cells and astrocytes in primary cultures and hippocampal slices." (PMID 38276297, 2023). "A study demonstrated that over-expression of S100B in glioma promoted tumor growth by CCL2(C-C motif ligand 2) upregulation and TAM chemoattraction in murine models." (PMID 36046652, 2022). "Further studies by our group showed that inhibiting S100B via administration of duloxetine (an SSNRI) abrogated glioma growth and reduced TAM infiltration." (PMID 34975408, 2021). "One of our first studies that analyzed S100B in relation to gliomas, found that S100B modulated STAT3 activity in microglia." (PMID 34975408, 2021). "In conclusion, the exogenous S100B in the glioma microenvironment is internalized into MSCs by both CME and lipid raft-mediated endocytosis." (PMID 34381770, 2021).
glioma (continued). "In conclusion, our findings show that clathrin and lipid rafts contribute to the internalization of S100B-Alexa488, which provides promising interventions for the safe application of MSCs in glioma therapy." (PMID 34381770, 2021). "The genes AQP4, BCAN, GFAP, PLP1, and S100B are part of the astrocytic, oligodendrocytic, or proneural glioma signatures." (PMID 34101353, 2021). "Firstly, the S100A11, S100A16, and S100B expression levels were significantly upregulated in glioma tissues than in normal controls from GEPIA database." (PMID 34712325, 2021). "There is growing evidence that the RAGE ligand S100B is another factor that plays a role in glioma progression." (PMID 32722137, 2020). "Low levels of S100B expressed by gliomas triggered STAT3 and blocked microglia and also macrophage activation." (PMID 32722137, 2020). "This cancer progression effect of STAT3 has been recognized in glioma cells in response to S100B/RAGE." (PMID 32443845, 2020). "We have shown here that the mere transfection specifically of the SOD1G93A gene in C6 glioma cells is sufficient to elicit an upregulation of S100B production and release." (PMID 28713206, 2017). "In conclusion, the majority of glioma patients have normal serum S100B values which remains within the normal limits throughout the course of the disease." (PMID 27401156, 2016). "The aim of our study was to assess the prognostic value in terms of survival and longitudinal dynamics of serum S100B for patients with newly diagnosed and recurrent glioma." (PMID 27401156, 2016). "Regarding the correlation of serum S100B levels and survival in glioma patients few data are available in literature." (PMID 27401156, 2016). "In the current study we found that the majority of newly diagnosed and recurrent glioma patients have serum S100B levels within normal limits." (PMID 27401156, 2016). "In glioma patients little is known about the prognostic value of serum S100B and its longitudinal behaviour during the course of the disease." (PMID 27401156, 2016). "The aim of this study was to prospectively evaluate the prognostic value and the longitudinal dynamics in terms of overall survival (OS) of serum S100B in patients with newly diagnosed and recurrent glioma during treatment with chemotherapy." (PMID 27401156, 2016). "C6 glioma cells expressing RAGE displayed increased s100B stimulated cell migration compared to mock transfected cells (1.9 fold increase, p = 0.03)." (PMID 24260107, 2013). "In this case, as well as in the case of glioma cell lines induced to acquire a differentiated phenotype by serum starvation, reexpressed S100B firstly appears to be located at the origin of cell extensions in proximity of F-actin bundles." (PMID 20827421, 2010). "In the context of gliomas, S100B can stimulate the phosphatidylinositol 3 -kinase/ protein kinase B (PI3K/Akt) and PI3K/RhoA pathways by interacting with Rous sarcoma virus-related tyrosine-protein kinase src (Src kinase), which is involved in the activation of astrocytes." (PMID 40243478, 2025). "One is that lactate signaling via HCAR1 for S100B secretion is less important in C6 glioma cells." (PMID 38276297, 2023). "Indeed, astrocytes and C6 glioma cells respond similarly to many harmful stimuli, such as LPS, with respect to TNFα and even S100B secretion." (PMID 38276297, 2023). "However, if we look at S100B secretion, C6 glioma cells exposed to FC behaved in an opposite manner to astrocytes." (PMID 38276297, 2023). "In C6 glioma cells, there was an increase in S100B protein secretion compared to the basal group (p = 0.0032), while in primary astrocyte cultures’ (p = 0.0002) acute hippocampal slices, we observed a decrease in S100B secretion compared to the basal group (p < 0.0001)." (PMID 38276297, 2023). "S100A8, S100A9 and S100B were highly expression in serum and may present as a marker correlated with survival and prognosis of glioma patients." (PMID 36046652, 2022).
glioma (continued). "Recently, several studies have indicated that serum levels of the S100B protein may be a valuable serum biomarker to predict the prognosis in glioma patients." (PMID 36046652, 2022). "Furthermore, previous studies have reported that risperidone increased S100B secretion from C6 glioma cells after 1-h treatment and increased S100B expression of primary cultured astrocytes after 24-h treatment." (PMID 35615587, 2022). "Furthermore, the S100B protein has been proposed to significantly contribute to glioma development by interacting with protein signaling pathways directly or indirectly." (PMID 36046652, 2022). "The link between S100B and glioma is being investigated by our group." (PMID 34975408, 2021). "The cancer-promoting effects of S100B were also declared in glioma, colon cancer and others." (PMID 34837947, 2021). "In addition, it has been demonstrated that poor prognosis in recurrent glioma patients correlates with high S100B levels." (PMID 34975408, 2021). "However, increased levels of S100B have been shown to upregulate pro-inflammatory pathways that can play a role in the pathogenesis of not only gliomas but also Alzheimer’s and epilepsy." (PMID 34975408, 2021). "S100B is a calcium-binding protein with a molecular weight of approximately 12 kDa that is highly expressed in multiple malignant tumors, such as glioma, melanoma, and breast cancer." (PMID 34381770, 2021). "Moreover, it has been revealed that high S100B levels correlate with poor prognosis in recurrent glioma patients." (PMID 32722137, 2020). "Aiming to verify whether the alteration of S100B and RAGE could depend on the mere presence of the ALS-linked SOD1G93A protein in astrocytes, we transiently overexpressed human SOD1G93A in C6 glioma cells." (PMID 28713206, 2017). "Furthermore, a former pilot study showed a correlation between high serum S100B concentrations and a shorter survival in a small population of glioma patients." (PMID 27401156, 2016). "Number of glioma colonies used in the S100B experiments for each exposure condition." (PMID 26869990, 2016). "Based on these results, we hypothesize that serum S100B can be helpful in predicting prognosis in glioma patients." (PMID 27401156, 2016). "Furthermore, we detected S-nitrosylation as an endogenous PTM of S100B protein in C6 glioma cells—a frequently used experimental model of astrocytes." (PMID 27159591, 2016). "We employed C6 glioma cells, a commonly used experimental model of astrocytes, to prove the hypothesis that S100B protein may be endogenously S-nitrosylated inside cells." (PMID 27159591, 2016). "Thus, we think that it is important to develop more potent S100B-inhibitors for glioma therapy." (PMID 32443845, 2020). "In recurrent glioma patients S100B might be of value in terms of prognostication of survival." (PMID 27401156, 2016). "Gliomasphere line specific (EGFR) and cell cycle markers (MKI67, TOP2A) dominated clustering and we noted enrichment of glioma stem cell (PTPRZ1, SOX2) and astrocytic markers (GFAP, S100B) in GS025." (PMID 38856710, 2024). "In our previous study, we developed an S100 family-based prognostic signature consisting of five genes of S100A11, S100A16, S100B, S100PBP and S100A13 for glioma patients." (PMID 37151881, 2023). "S100B, a RAGE ligand that promotes tumorigenesis by promoting IL-6 expression and STAT-3 activation, is abundantly expressed in gliomas." (PMID 36613714, 2022).
glioma (continued). "RAGE interactions with S100B and S100A9 are well characterized within glioma, but in addition to these two proteins, 11 other S100 members have also been demonstrated to interact with RAGE." (PMID 34975408, 2021). "We also confirmed that increased S100B expression led to RAGE upregulation, thus confirming the presence of a positive feedback loop between RAGE and its ligands in gliomas." (PMID 34975408, 2021). "The authors treated mouse glioma cells (GL261) with duloxetine at a dose of 30 mg/kg by oral gavage for 14 days and determined that duloxetine inhibited S100B production and inhibited the growth of intracranial GL261 gliomas." (PMID 32443845, 2020). "In a high-throughput screening cell-based S100B promoter-driven luciferase reporter assay, duloxetine was identified to inhibit S100B and CCL2 production in a mouse glioma model." (PMID 32722137, 2020). "Recently, it has been reported that strong expression of glial markers, including GFAP, S100β, and OLIG2, and elevated p-ERK levels are observed in the glioneuronal tumors or glioma of NS patients." (PMID 32493428, 2020). "Moreover, the cell morphology of primary human glioma cells, U251-MG and U87-MG cells were evaluated through the label of GFAP and S100B proteins." (PMID 34422645, 2021). "For the GEPIA-derived cohort, the expression levels of S100A11, S100A16, and S100B in low-grade glioma (LGG) and GBM samples increased compared with those in noncarcinoma samples, while S10013 in LGG tissue was upregulated in normal tissues." (PMID 34712325, 2021). "Also, S100B fostered a cellular microenvironment that upregulates the CCL2 chemokine, allowing for migration of TAMs into gliomas." (PMID 34975408, 2021). "S100B may also encourage glioma growth by TAM chemoattraction and therefore, infiltration into gliomas through the upregulation of CCL2." (PMID 32722137, 2020). "Other studies have reported an increase in cell content of S100B in C6 glioma cells after 24 h of exposure to IL-1β or no change in astrocyte cultures after 48 h and a decrease in S100B content in cultured astrocytes after 3 days of exposure to TNFα." (PMID 21970823, 2011). "However, it does not explain the increase in S100B secretion in C6 glioma cells in the presence of FC." (PMID 38276297, 2023). "Serum S100B does not seem to have prognostic value in newly diagnosed glioma patients." (PMID 27401156, 2016). "Third, the genetic profile of our glioma patients was not assessed as a confounding factor in this study, which may have biased the results concerning the prognostic value of serum S100B." (PMID 27401156, 2016). "Serum S100B levels do not seem to have prognostic value in newly diagnosed glioma patients." (PMID 27401156, 2016).